CXCL12 (C-X-C motif chemokine ligand 12)
Diseases named in the same sentence as CXCL12 in open-access papers (continued):
Sharing a sentence is not in itself a finding about the gene and the disease.
cavernous hemangioma (1 paper, 2022). A hemangioma characterized by the presence of cavernous vascular spaces. "The results suggested that: 1) the ligand-receptor interactions between CXCL12 and CXCR4 play a significant role in the immune responses in cavernous hemangiomas; and 2) the high expression of BTNL9 may cause checkpoint blockade in BTNL9+EC through the binding of BTNL9 to T-cells." (PMID 35865633, 2022).
cervical tumor (1 paper, 2021). "A cervical tumor invades in adjacent tissues and subsequently into distant organs initiated by the expression of CXCR4 through the link of another factor CXCL12." (PMID 33946372, 2021).
chronic lymphocytic thyroiditis (1 paper, 2022). "Myeloid cells express chemokines (CXCL12 and CXCL10) as chemoattractants to recruit T cells expressing their receptors (CXCR4 and CXCR3), which is consistent with the pathological findings indicating chronic lymphocytic thyroiditis in P1 and P2 patients." (PMID 35515000, 2022). "Myeloid cells expressed genes (CXCL10 and CXCL12) for chemokines as chemoattractants to recruit T cells expressing CXCR4 and/or CXCR3 in T1 and T2 samples, but not in T3, which was in accordance with the histological assessment that indicated chronic lymphocytic thyroiditis in T1 and T2 samples." (PMID 35515000, 2022).
CNS leukemia (1 paper, 2020). "Targets of these microRNAs included proteins associated to CNS leukemia, e.g., Zeta Chain of T Cell Receptor Associated Protein Kinase 70 (ZAP70) and C-X-C modif chemokine ligand 12 (CXCL12)." (PMID 32752027, 2020).
cocaine addiction (1 paper, 2015). "The results showed that the concentrations of chemokine (C-C motif) ligand 2/monocyte chemotactic protein-1 (CCL2/MCP-1) and chemokine (C-X-C motif) ligand 12/stromal cell-derived factor-1 (CXCL12/SDF-1) were only affected by history of cocaine addiction." (PMID 25762940, 2015). "Similarly, history of cocaine addiction (F1,122 = 7.72, p = 0.006) had a significant main effect on CXCL12 concentrations." (PMID 25762940, 2015).
colon adenoma (1 paper, 2017). An adenoma that arises from the colon. "CXCL12 expression was analyzed at the protein and mRNA levels in an independent cohort that included 30 colon adenomas and 46 sporadic MSS carcinomas." (PMID 28418886, 2017). "CXCL12 expression was measured in human colon adenomas and carcinomas with transcriptome array and RT-qPCR." (PMID 28418886, 2017). "We thus evaluated CXCL12 expression in a large cohort of colon adenomas and carcinomas, investigated for an epigenetic mechanism controlling its expression and evaluated the impact of CXCL12 levels on cell migration and tumor growth." (PMID 28418886, 2017).
craniosynostosis (1 paper, 2025). Craniosynostosis is defined as the premature fusion of one or more cranial sutures leading to secondary distortion of skull shape resulting in skull deformities with a variable presentation. "While our study identifies Tgf-β1 as a key SASP factor driving the osteogenic differentiation of SPC in craniosynostosis, our transcriptomic data also indicate the significant upregulation of other SASP members, such as Vegfa and Cxcl12." (PMID 41390905, 2025).
demyelinating disease (1 paper, 2016). A broad group of disorders that affect the myelin sheaths that cover the neurons. "However, few studies have analyzed the potential function of CXCL12 in the context of myelin or neuronal repair in CNS inflammatory and demyelinating diseases, such as EAE/MS." (PMID 26747276, 2016).
dengue virus infection (1 paper, 2015). "In wild-type mice, mast cells responding to dengue virus infection upregulated chemokine expression (RANTES/CCL5, SDF-1/CXCL12, and fractalkine/CX3CL1), and mediated recruitment of NKT cells (CD3+NK1.1+) into the skin at sites of dengue virus infection." (PMID 26074921, 2015).
dry eye (1 paper, 2018). "Concerning the CXCR4 ligand, we observed an increasing trend in mRNA CXCL12 levels in dry eye patients." (PMID 29673232, 2018). "Again, these cell populations increased in dry eye patients, explaining the higher levels of CXCL12 and CXCR4 in patients suffering from DED." (PMID 29673232, 2018).
dysplasia (1 paper, 2021). A usually neoplastic transformation of the cell, associated with altered architectural tissue patterns. "While the expression of CXCL12 (SDF-1α) and CXCR4 progressively increased from oral leukoplakia (OLK) to dysplasia to frank malignancy, hyperactivation of this axis in HNSCC is associated with aggressive tumors, regional and distant metastasis, and lower DFS." (PMID 33925575, 2021).
endometrial tumors (1 paper, 2019). "This axis does not seem to be related to disease progression in endometrial tumors as CXCL12 is poorly secreted in the tumor microenvironment." (PMID 31105699, 2019). "All together, we showed that both cytokine and chemokine production in the endometrial tumors may participate to the alteration of NK cell function, as IL-6 and IL-1β are increased in the tumor, and recruitment, as chemoattractants CCL27, CXCL12, and CCL21 are significantly reduced in the tumor." (PMID 31105699, 2019).
enterovirus infection (1 paper, 2019). "Following enterovirus infection, and in the absence of apical CXCL12, the migration of Th1 effector cells was significantly enhanced." (PMID 31752904, 2019). "Clinical studies revealed that enterovirus infection of the central nervous system (CNS) resulted in increased levels of inflammatory cytokines within the cerebrospinal fluid (CSF), such as INF-γ, IL-6, and CXCL12, accompanied by influx of neutrophils and T cells." (PMID 31752904, 2019). "To decipher the specific effects of the enteroviral infection, we focused on experiments without CXCL12, since the latter may have potential strong alterations on several integrins." (PMID 31752904, 2019).
Epileptic spasm (1 paper, 2022). A sudden flexion, extension, or mixed extension-flexion of predominantly proximal and truncal muscles that is usually more sustained than a myoclonic movement but not as sustained as a tonic seizure. "Only CXCL12 was significantly different in epileptic spasms compared to OND group (decreased, p<0.0001) (Mann Whitney U test)." (PMID 36174397, 2022).
erythroleukemia (1 paper, 2020). Acute erythroid leukemia characterised by the presence of at least 50% erythroid precursors and at least 20% myeloblasts in the bone marrow. "To achieve this goal, we defined the effects of FtH knock down in the induction of EMT markers, activation of CXCR4/CXCL12 signaling pathway and migration of K562 erythroleukemia cells, and further attempted to understand the molecular mechanisms involved." (PMID 32432042, 2020). "Here, we demonstrate that the alteration of iron homeostasis and the consequent increase of redox metabolism, mediated by the stable knock down of ferritin heavy chain (FtH), enhances the expression of CXCR4 in K562 erythroleukemia cells, thus promoting CXCL12-mediated motility." (PMID 32432042, 2020).
essential thrombocythemia (1 paper, 2020). A chronic myeloproliferative neoplasm that involves primarily the megakaryocytic lineage. "Moreover, patients with polycythemia vera (PV), essential thrombocythemia (ET), and primary myelofibrosis (pMF) exhibited characteristic localization patterns of CXCL12‐positive cells in the bone marrow." (PMID 31709722, 2020).
fluorosis (1 paper, 2024). "Therefore, the present study aimed to further investigate the role of the CXCL12/CXCR4 signaling axis and the related inflammatory factors IL-1β, TNF-α, IL-6 and NF-κB in the mechanism of fluorosis-induced liver injury at the cellular level." (PMID 38905184, 2024).
follicular thyroid carcinoma (1 paper, 2020). "The biological roles of CXCL12 also were founded in THCA, in which CXCR4/CXCR7/CXCL12 axis offer new valuable insight into the oncogenesis of metastatic follicular thyroid carcinoma." (PMID 32714651, 2020).
food allergy (1 paper, 2021). Gastrointestinal disturbances, skin eruptions, or shock due to allergic reactions to allergens in food. "Here, our results show the association between DNAm levels with food allergy for CXCL12, CCR7, RUNX1, and CD3E." (PMID 33571165, 2021).
fracture (1 paper, 2022). "Similarly, levels of CXCL12 have been shown to increase following bone fracture." (PMID 35831901, 2022).
Graves disease (1 paper, 2021). Graves' disease is an autoimmune disorder that leads to overactivity of the thyroid gland (hyperthyroidism).It is caused by an abnormal immune system response that causes the thyroid gland to produce too much thyroid hormones. "Two of these—Cxcl12 and Slc16a2—are particularly noteworthy because of potential links to the pathogenesis of Graves disease, in which inflammation and adipogenesis are selectively observed in retrobulbar fat, but not other adipose tissues." (PMID 33542375, 2021).
hairy cell leukemia (1 paper, 2015). Hairy cell leukemia (HCL) is a rare type of leukemia in which abnormal B-lymphocytes are present in the bone marrow, spleen and peripheral blood. "Similar inhibitory effects on proliferation and survival, CCL3/CCL4 secretion, and CXCL12 signaling occur in hairy cell leukemia (HCL) treated with ibrutinib." (PMID 26022368, 2015).
hantavirus infection (1 paper, 2017). "Additionally, we have shown that CXCL12, a potent chemoattractant for mononuclear leukocytes, is upregulated in patients with hantavirus infection." (PMID 28572804, 2017).
hemangioblastoma (1 paper, 2016). "This is the first study in which expression of CXCR4, CXCL12, and VEGFA is compared in both sporadic and VHL associated hemangioblastoma patients." (PMID 26920352, 2016). "The finding that CXCR4 expression was higher in sporadic hemangioblastomas is striking as in VHL-disease a germline mutation in VHL leads to a defect VHL protein which results in enhanced transcription of CXCR4, its ligand CXCL12 as well as VEGFA." (PMID 26920352, 2016). "Compared to normal surrounding tissue CXCR4, CXCL12, and VEGFA were overexpressed in hemangioblastomas." (PMID 26920352, 2016). "This study shows that CXCR4, CXCL12, and VEGFA are all overexpressed in stromal hemangioblastoma cells compared to normal surrounding brain tissue." (PMID 26920352, 2016). "We aimed to determine in VHL-related and sporadic hemangioblastomas CXCR4, CXCL12, and VEGFA protein expression and to correlate this to hemangioblastoma size and expression in normal surrounding tissue." (PMID 26920352, 2016). "Sporadic and VHL-related hemangioblastomas had the same level of CXCL12 expression, with strong expression in 75 % (12 out of 16) of sporadic hemangioblastomas and in 81 % (13 out of 16) of VHL-related hemangioblastoma cells." (PMID 26920352, 2016). "CXCR4, CXCL12, and VEGFA were all overexpressed in hemangioblastomas as compared to normal surrounding tissue." (PMID 26920352, 2016). "Hemangioblastomas overexpress CXCR4, CXCL12, and VEGFA compared to normal surrounding tissue." (PMID 26920352, 2016). "Earlier studies in VHL related hemangioblastoma found upregulated CXCR4, CXCL12, and VEGFA." (PMID 26920352, 2016). "Therefore, the aim of this study was to investigate CXCR4, CXCL12, and VEGFA protein expression in VHL-related and sporadic hemangioblastomas and to correlate this to size as measured by MRI before surgery to investigate possible differences between VHL-related and sporadic hemangioblastoma." (PMID 26920352, 2016).
hemangiosarcoma (1 paper, 2015). "In vitro, CXCL12 promoted cell migration and invasion of hemangiosarcoma cells, and these responses were also sensitive to the CXCR4 antagonist, AMD3100." (PMID 29061946, 2015). "In hemangiosarcoma, the heterogeneous expression of CXCR4 and CXCL12 was reported in hemangiosarcoma cell lines and whole tumor tissues by transcriptome analysis." (PMID 29061946, 2015). "Considering the proposed bone marrow origin of hemangiosarcoma, hemangiosarcoma cells expressing CXCR4 on their cell surface may represent a progenitor population that is maintained by CXCL12-abundant reticular cells in this niche." (PMID 29061946, 2015). "The potential also exists that CXCR4 and CXCL12 expression may be regulated through beta adrenergic signaling, and beta blockade may prevent the expansion of hemangiosarcoma progenitor cells from the bone marrow or the migration of these cells to CXCL12-rich sites, reducing metastatic spread." (PMID 29061946, 2015).
hepatitis B (1 paper, 2021). "Studies have shown that prevaccination levels of CXCL11 and CXCL12 in healthy individuals and CXCL13 in HIV+ subjects may predict hepatitis B-vaccine response." (PMID 33431890, 2021).
HIV-associated neurocognitive disorder (1 paper, 2025). HIV-associated neurocognitive disorder (HAND) remains a common complication of HIV infection in the combination antiretroviral therapy (ART) era. "Some studies have reported gender-related differences in the concentrations of CXCL-12 and CXCL-10 in serum and plasma samples from patients with inflammatory responses due to spinal cord injury and HIV-associated neurocognitive disorder (HAND)." (PMID 39861878, 2025).
hypercortisolism (1 paper, 2021). "Further studies are mandatory to assess whether hypercortisolism is somehow associated with a reduction of CXCL12 levels and a decreased local immune response in ACC." (PMID 34834449, 2021).
idiopathic inflammatory myopathies (1 paper, 2025). "Several inflammatory myopathies have been associated with CCL2, MCP-3 and RANTES, and CXCL12 and CCL2 have been shown to be increased in idiopathic inflammatory myopathies." (PMID 41348866, 2025).
IgA nephropathy (1 paper, 2024). "Correlation between the urine TWEAK, CXCL1, CXCL12, MCP1, and TRAIL protein with severity of IgA nephropathy." (PMID 39492831, 2024).
Impaired glucose tolerance (1 paper, 2022). An abnormal resistance to glucose, i.e., a reduction in the ability to maintain glucose levels in the blood stream within normal limits following oral or intravenous administration of glucose. "Because systemic hypoxia may also affect the expression of cytokines in skeletal muscle, we measured CXCL12 mRNA in skeletal muscle biopsies collected from individuals with either normal or impaired glucose tolerance after acute exercise under hypoxic conditions." (PMID 36070371, 2022).
inherited thrombocytopenia (1 paper, 2020). An instance of thrombocytopenia that is inherited. "SDF-1α-CXCR4 localized to lipid rafts in the platelet membrane trigger platelet reactivity, while decreased surface expression of CXCR4 in patients with inherited thrombocytopenia corroborates with impaired CXCL12/SDF1α-triggered platelet aggregation." (PMID 33114406, 2020).
intervertebral disc degeneration (1 paper, 2022). "Study on intervertebral disc degeneration has shown that miR-623 directly bound CXCL12 to reduce levels of inflammatory factors in LPS-injured nucleus pulposus cells." (PMID 35919038, 2022).
intestinal tumor (1 paper, 2017). "We attempted to demonstrate whether the loss of CXCL12 expression observed in human carcinomas would also be found in mouse models of intestinal tumors." (PMID 28418886, 2017). "Regarding the CXCL12 loss, it results from a promoter acetylation defect for the large majority of carcinomas and treating APC mutant mice with a HDAC inhibitor importantly reduces the intestinal tumor development." (PMID 28418886, 2017). "In vivo, valproate diminished (65%) the number of intestinal tumors in APC mutant mice, slowed down xenograft tumor growth concomitant to restored CXCL12 expression." (PMID 28418886, 2017). "Nevertheless, VPA could reduce ectopic tumor growth in vivo as well as the number of intestinal tumors in APC mutant mice, and this effect was concomitant to the re-expression of CXCL12." (PMID 28418886, 2017).
intestinal type carcinoma (1 paper, 2010). "The CXCL12 expression in tumour cells had no impact on patient survival (entire group: p = 0.830; intestinal type carcinoma: p = 0.766; diffuse type carcinoma: p = 0.817)." (PMID 20386750, 2010).
liver dysfunction (1 paper, 2025). "Other potential surrogates of liver dysfunction and fibrosis include hepatically derived factors elevated in patients with RHF, such as bile acids, sCD163, and CXCL12." (PMID 40738518, 2025).
liver failure (1 paper, 2015). A liver disease characterized by the liver losing or has lost all of its function. "It is also interesting to note that ADIPOQ, β-NGF, CXCL1, CXCL9, CXCL12, IL-16, and PECAM-1 are up-expressed only in those CHC and HCC patients who present a liver failure, and, hence, linkable to the necro-inflammatory activity of the liver." (PMID 26226632, 2015).
memory impairment (1 paper, 2025). "Specific targets, such as NFKBIA, Cxcl12 (C‐X‐C motif chemokine ligand 12) and Vav3, along with key signalling pathways like chemokine, Wnt and NF‐kappa B, may mediate the effects of exercise on METH‐induced learning and memory impairments." (PMID 40782057, 2025).
metastatic prostate carcinoma (1 paper, 2013). A carcinoma that arises from the prostate gland and has spread to other anatomic sites. "Implication of the CXCR4/CXCL12 axis in regulating the migration of human T and NK cells to BM has been reported in several studies, including in human metastatic prostate cancer." (PMID 23755121, 2013).
Mucopolysaccharidosis I (1 paper, 2016). "Finally, it was demonstrated that accumulated overly sulfated extracellular HS, in patients suffering from Mucopolysaccharidosis I, alters cytokine gradient formation since they abnormally bind and sequester CXCL12." (PMID 26742480, 2016).
mycobacterial infection (1 paper, 2024). "Furthermore, double knockdown of miR-126 and either cxcl12a or ccr2 reduced cell death and from miR-126 knockdown alone, demonstrating that the Cxcl12/Ccl2/Ccr2 signalling axis is driving the miR-126 knockdown-associated increase in ineffective macrophage recruitment to mycobacterial infection." (PMID 38307625, 2024). "We have previously identified an miRNA-mediated Cxcr4/Cxcl12 signalling axis which increased protective neutrophil responses in mycobacterial infection." (PMID 38307625, 2024). "We link infection-induced miR-126 to Tsc1 via activation of the mTOR pathway and improved macrophage function because of regulation of a Cxcl12/Ccl2/Ccr2 signalling axis during the early stages of mycobacterial infection." (PMID 38307625, 2024).
myeloid malignancies (1 paper, 2025). "Analysis of the glycosaminoglycan analog dociparstat sodium reveals significant activity in myeloid malignancies, mediated by specific interference with CXCL12/CXCR4 signaling cascades." (PMID 40143176, 2025).
myelopathies (1 paper, 2024). "For CXCL12, ROC analysis indicated an AUC value of 0.99 ± 0.005 (95% CI 0.98–1.00, P = 0.000) for myelopathies, with the optimal cut-off at 451.1 pg/mL determined by the Youden index (0.95; sensitivity of 100%; specificity of 95.7%)." (PMID 39188590, 2024).
nasal polyps (1 paper, 2021). "In nasal polyps from patients with AR, the expressions of lnc-CXCL12-4, CXCL12, and CXCR4 were increased significantly compared to those from nasal polyps without AR." (PMID 33836777, 2021).
nerve sheath tumors (1 paper, 2024). "The link of CXCL12 and CX3CL1 expression to human nerve sheath tumors has also been reported in recent literature." (PMID 40115159, 2024).
neuromyelitis optica (1 paper, 2018). A rare inflammatory disease of the central nervous system characterized mainly by attacks of uni- or bilateral optic neuritis (ON) and acute myelitis. "The concentration of CXCL12 was decreased in pOMS, N-methyl-d-aspartate receptor (NMDAR) encephalitis, pAnti-Hu/ANNA-1 paraneoplastic syndrome, and neuromyelitis optica (NMO), but increased in pMOG, adult AE, and neuropsychiatric systemic lupus erythematosus (NPSLE)." (PMID 29670611, 2018).